CADM2 (cell adhesion molecule 2)
Description:
Adhesion molecule that engages in homo- and heterophilic interactions with the other nectin-like family members, leading to cell aggregation. Important for synapse organization, providing regulated trans-synaptic adhesion. Preferentially binds to oligodendrocytes. [Isoform 5]: (Microbial infection) Induces cell fusion in neuron infected by a neuropathogenic strain of measles. Interacts with measles hemagglutinin to trigger hyperfusogenic F-mediated membrane fusion and presumably transsynaptic cell-to-cell transmission of the virus.
Synonyms: IgSF4D; NECL-3; SynCAM 2; NECL3; SynCAM2; SynCAM-2
Tractability: Antibody: UniProt places it where antibodies can reach, with high confidence; its Gene Ontology location is reachable by antibodies, with high confidence; UniProt predicts a signal peptide or a membrane-spanning region. PROTAC: ubiquitination databases record sites on it; its protein half-life has been measured.
Safety:
Unwanted effects reported when the protein is acted on. In parentheses: how it was acted on, where the effect was seen, and who reports it.
alcoholism (source: ClinPGx)
Gene: Protein-coding gene on chromosome 3 (84,958,989 to 86,074,429, forward strand). Ensembl gene ENSG00000175161.
Subcellular location: Cell membrane; Synapse; Cell projection, axon
Pathways (Reactome):
Cell-Cell communication: Adherens junctions interactions
Gene Ontology:
Molecular function: protein binding
Biological process: homophilic cell-cell adhesion
Cellular component: neuronal cell body membrane; plasma membrane; axon; synapse
Genetic constraint (gnomAD): Loss-of-function variants: 11 observed, 35.26 expected, observed/expected ratio (o/e) 0.31, 90% interval 0.19 to 0.52. The upper end of that interval is the gene's LOEUF score, 0.52, which puts it in group 2 of 6, group 1 being the genes least tolerant of losing a copy. Missense variants: 311 observed, 425.64 expected, observed/expected ratio (o/e) 0.73, 90% interval 0.67 to 0.8. Synonymous variants: 187 observed, 154.57 expected, observed/expected ratio (o/e) 1.21, 90% interval 1.07 to 1.37.
Homologues: Orthologues: mouse Cadm2 (97% identical), chimpanzee CADM2 (96% identical), macaque CADM2 (96% identical), dog CADM2 (96% identical), rabbit CADM2 (95% identical), pig CADM2 (94% identical), rat Cadm2 (92% identical), guinea pig CADM2 (86% identical), tropical clawed frog cadm2 (80% identical), zebrafish cadm2b (68% identical), zebrafish cadm2a (64% identical), Drosophila melanogaster Fas3 (20% identical). Paralogues in human: CADM3 (50% identical), CADM1 (45% identical), CADM4 (36% identical), NECTIN1 (22% identical), NECTIN4 (21% identical), NECTIN2 (21% identical), NECTIN3 (21% identical), PVR (20% identical), CRTAM (16% identical), CD226 (15% identical), CD200 (12% identical), TIGIT (10% identical), and 2 more.
Diseases named in the same sentence as CADM2 in open-access papers:
CADM2 is named in the same sentence as 69 diseases in open-access papers, as found by Europe PMC text mining. Sharing a sentence is not in itself a finding about the gene and the disease. The quoted sentences say what the papers report.
Obesity (23 papers, 2015 to 2026). Accumulation of substantial excess body fat. "Recent studies show that reducing CADM2 expression can reverse several traits associated with the metabolic syndrome including obesity, insulin resistance, and impaired glucose homeostasis." (PMID 37904118, 2023). "Overall, the risk allele in rs13078960 SNP for CADM2 predisposes to obesity and incommodes the weight loss process in the pediatric population with overweight and obesity." (PMID 36986146, 2023). "Genome-wide association studies have identified SNPs in CADM2 (rs13078960, rs1307880) as obesity susceptibility loci, similarly with its related family member CADM1." (PMID 36986146, 2023). "The CpG site (cg11700298) annotated to cell adhesion molecule 2 (CADM2)] was selected because polymorphism in this gene has been associated with obesity and type 2 diabetes." (PMID 36585686, 2022). "In animal models, increased Cadm2 expression is associated with obesity, while knockout or loss of Cadm2 prevents obesity, improves insulin sensitivity and protects mice from developing diabetes." (PMID 33424774, 2020). "GWAS studies have identified SNPs near CADM2 that are associated with higher expression of CADM2, and the development of obesity." (PMID 33424774, 2020). "When considering the effects of CADM2 variants on both psychological and obesity traits, a possible explanation is mediated pleiotropy, for example through physical exercise." (PMID 31089183, 2019). "CADM2 has previously been associated with psychological traits and obesity." (PMID 41243181, 2026). "The strongest signal was observed on chromosome 3 at the CADM2 region (index SNP rs34495106, pmeta = 3.02 × 10− 19), a critical gene associated with a range of behavioral and metabolic traits, including physical activity, alcohol and cannabis use, and obesity." (PMID 35250867, 2022). "The CADM2 gene encodes a member of the synaptic cell adhesion molecules 1 family, and is associated with a range of behavioral and metabolic traits, such as educational attainment, alcohol and obesity." (PMID 32922442, 2020). "Associations between CADM2 SNPs and obesity have previously been reported and were observed here." (PMID 31089183, 2019). "CADM2 has been associated with a range of behavioural and metabolic traits, including physical activity, risk-taking, educational attainment, alcohol and cannabis use and obesity." (PMID 31089183, 2019). "In obese mice, expression of CADM1 and CADM2 increased, and Cadm1 loss protected mice from obesity." (PMID 29966015, 2018). "It has been shown that CADM2 is expressed in nervous system of zebra fish, implicating that the CADM2 is a conserved evolutionarily gene and may be implicated in various physiological processes related to obesity in humans." (PMID 26683835, 2015). "CADM2 is also known as a factor linking psychological/behavioral traits and obesity, as well as the brain and adipose tissues." (PMID 40176157, 2025). "Further research into the role of CADM2 during obesity lifestyle interventions is necessary, while the ketogenic diet approach seems to be a promising topic for research." (PMID 36986146, 2023). "In contrast, biological pleiotropy is supported by the body of evidence indicating a role for CADM2 in psychological and obesity traits from other types of studies." (PMID 31089183, 2019). "Mouse models demonstrate a clear effect of Cadm2 on obesity and gluco-metabolic parameters: A global Cadm2-knockout mouse demonstrated reduced body weight, improved insulin sensitivity and improved glucose tolerance." (PMID 31089183, 2019). "CADM2 is expressed in some brain regions implicated in the present study, namely the frontal cortex (BA9), and has been associated with cognition, pain, impulsivity, substance use, other risky behaviors, obesity, and other metabolic traits." (PMID 38746260, 2024). "Moreover, CADM2 is related to a series of behavioral and metabolic features, including physical activity, adventure, educational level, and obesity." (PMID 34093644, 2021).
Obesity (continued). "Obesity risk variants were associated with increased CADM1 and CADM2 expression in the hypothalamus with a complex interplay of CADM1 and CADM2." (PMID 32373164, 2020).
breast carcinoma (8 papers, 2015 to 2025). "In silico analyses likely indicate quercetin as a CDK2 inhibitor in ER+ breast cancer and that quercetin can re-sensitize breast cancer cells to palbociclib by governing the circHIAT1/miR-19a-3p/CADM2 axis." (PMID 40244377, 2025). "In another research, the circHIAT1/miR-19a-3p/CADM2 axis affected the epithelial-to-mesenchymal transition (EMT) and resistance to palbociclib with circHIAT1 and CADM2 downregulation in breast cancer tissues and cell lines and miR-19a-3p upregulation." (PMID 40244377, 2025). "FOXO3a controls Twist to mediate the miR10b/CADM2/FAK/AKT axis to suppress EMT in breast cancer." (PMID 38505423, 2024). "For instance, CADM2 inhibits breast cancer EMT and metastasis." (PMID 38126999, 2023). "Furthermore, CADM2 has been shown to prevent the progression of cancers, such as retinoblastoma, breast cancer, glioma." (PMID 38126999, 2023).
glioma (7 papers, 2021 to 2025). A benign or malignant brain and spinal cord tumor that arises from glial cells (astrocytes, oligodendrocytes, ependymal cells). "CADM2 is significantly underexpressed in glioma cells, a finding that confirms CADM2 as a promising target for miR-25." (PMID 35922753, 2022). "CADM2 has been reported to be a tumor suppressor in hepatocellular carcinoma and in glioma, and has been shown to inhibit the migration and invasion of tumor cells via the FAK/AKT signaling pathway." (PMID 34885212, 2021). "The predominant majority of rat glioma 101.8 tumor cells expressed Cadm2, Cdkn1b, and Ero1a." (PMID 41009560, 2025). "Additionally, it enhances cerebral metastases within non-small cell lung cancer cases by triggering epithelial-mesenchymal transition (EMT) CADM2 suppresses glioma growth, migration, and invasion." (PMID 37228062, 2023). "Additionally, the upregulation of CADM2 promotes glioma cell proliferation and migration." (PMID 38126999, 2023). "Cell adhesion molecule 2 (CADM2) is more expressed in subgroup 1, involved in maintenance of cell adhesion and tumor suppression, inhibiting glioma proliferation, migration, and invasion." (PMID 39417309, 2025).
Anxiety (6 papers, 2018 to 2023). Intense feelings of nervousness, tension, or panic often arise in response to interpersonal stresses. "In the PheWAS, CADM2 variants were associated with decreased risk for externalizing psychopathology, but also increased risk for internalizing psychopathology (anxiety, depression, OCD)." (PMID 37173343, 2023). "Interestingly, the largest GWAS study identified six genetic susceptibility loci that were significantly associated with IBS, four of which were located in genes associated with mood and anxiety (NCAM1, CADM2, PHF2/FAM120A, DOCK9)." (PMID 36071849, 2022). "Interestingly, Cadm2 did not have more general effects on mouse behavior; for instance, we did not observe deficits in anxiety-like behavior or general motivation, as some of the human PheWAS findings revealed." (PMID 37173343, 2023).
prostate carcinoma (6 papers, 2015 to 2023). A carcinoma that arises from epithelial cells of the prostate gland. "Among these, we highlighted that the tumor suppressor gene CADM2, which encodes a cell adhesion molecule, has been associated with prostate cancer, and its main mechanism of dysregulation is mediated by gene hypermethylation." (PMID 37987361, 2023). "CADM2 acts as a tumour suppressor in renal cell carcinoma, prostate cancer and hepatocellular carcinoma, and has been reported promoting brain metastasis in lung cancer and proposed as a potential molecular target." (PMID 36045381, 2022). "Hypo-expression of CADM2 gene expression has been observed in prostate cancer, ovarian cancer, lymphoma, melanoma and liver cancer." (PMID 29506532, 2018). "Previous studies report that CADM2 acts as a tumor suppressor in prostate cancer and renal cell carcinoma progression." (PMID 29506532, 2018). "Additionally, EGFR was amplified in the MCR of 7p11.2, whereas CADM2, which has been identified as a tumor suppressor gene in prostate cancer, was deleted in the MCR of 3p12.1." (PMID 26386145, 2015). "In addition, CADM2 inhibits tumour progression in prostate cancer." (PMID 32352014, 2020).
hepatocellular carcinoma (5 papers, 2018 to 2023). A malignant tumor that arises from hepatocytes. "Liver fibrosis-derived exosomal miR-106a-5p facilitates the malignancy by targeting SAMD12 and CADM2 in hepatocellular carcinoma." (PMID 38098508, 2023). "miR-10b/CADM2 regulates hepatocellular carcinoma cells’ EMT activity, together with migratory capabilities through the focal adhesion kinase (FAK)/AKT signaling pathway." (PMID 37228062, 2023). "Hypo-expression of CADM2 gene expression has been observed in several cancers including hepatocellular carcinoma (HCC)." (PMID 29506532, 2018). "In hepatocellular carcinoma cells, miR-10b directly targets CADM2." (PMID 37228062, 2023).
depression (4 papers, 2019 to 2025). "We also pointed to a genetic association with psychiatric phenomena like psychosis, depression, ADHD, and SUDs, observed through several mutual genes, such as CADM2, TCF4, LINC02758, and CD47, and via genetic correlations." (PMID 40736093, 2025). "A common biological mechanism, such as CADM2, might also be consistent with the recent observation of a bi-directional link between depression and obesity." (PMID 31089183, 2019).
schizophrenia (4 papers, 2022 to 2025). A major psychotic disorder characterized by abnormalities in the perception or expression of reality. "Other genome-wide significant SNPs are in genes associated with schizophrenia (rs6125539; 4.72 × 10−09; CSE1L) and impulsivity (rs1248860; 9.51 × 10−09; CADM2)." (PMID 38811692, 2024).
Alzheimer disease (3 papers, 2021 to 2022). A progressive, neurodegenerative disease characterized by loss of function and death of nerve cells in several areas of the brain leading to loss of cognitive function such as memory and language. "Links to genes implicated in Alzheimer’s disease were also found in the results of the gene expression network analysis for CADM2 identified in the previous CHARGE GWAS of processing speed." (PMID 34864818, 2021).
autism (3 papers, 2014 to 2021). Persistent deficits in social interaction and communication and interaction as well as a markedly restricted repertoire of activity and interest as well as repetitive patterns of behavior. "CADM2 is located within the 4th most extreme outlier region and is a synaptic cell adhesion molecule whose flanking regions show reduced homozygosity in autism patients." (PMID 26943675, 2016). "We confirmed several loci responsible for Autism and Pervasive Developmental Disease including MACROD2, ITGB3, CADM2, and GRIK2." (PMID 25477900, 2014).
dementia (3 papers, 2022 to 2025). Loss of intellectual abilities interfering with an individual's social and occupational functions. "The results of a GWAS of non-dementia older adults indicate that the CADM2 gene is associated with executive function and information processing speed, both of which are related to cognitive function." (PMID 40893940, 2025). "Multiple GWAS have identified that CADM2 was associated with the cognitive ability, suggesting a potential role of CADM2 in dementia." (PMID 35509074, 2022).
esophageal squamous cell carcinoma (3 papers, 2024 to 2026). Esophageal squamous cell carcinoma (ESCC) is a type of esophageal carcinoma (EC) that can affect any part of the esophagus, but is usually located in the upper or middle third. "In esophageal squamous cell carcinoma (ESCC), the cell adhesion molecule CADM2 plays a significant role in tumor suppression." (PMID 41476448, 2025). "CADM2 over-expression could suppressed the EMT and cell proliferation of esophageal squamous cell carcinoma cells by repressing AKT signaling pathway." (PMID 38990915, 2024).
liver cancer (3 papers, 2018 to 2023). An epithelial or non-epithelial malignant neoplasm that arises from the liver. "SAMD12 and CADM2 were diminished in liver cancer cell lines, and their knockdown of them exacerbated the proliferation capacities of liver cells in vitro." (PMID 37228062, 2023). "What’s more, the data from GEO (Gene Expression Omnibus) database also indicate that the expression level of CADM2 in liver cancer with venous metastasis is apparently lower than that in those not transferred in the vein." (PMID 29506532, 2018). "The expression of CADM2 in liver cancer samples with venous metastasis was significantly lower than those without venous metastasis." (PMID 29506532, 2018). "The influence of CADM2 on EMT of liver cancer cells is further studied through FAK/AKT pathway." (PMID 29506532, 2018). "Therefore, we also analyzed promoter methylation of CADM2 in liver cancer tissues using TCGA data." (PMID 29506532, 2018).
colorectal cancer (2 papers, 2022 to 2023). A primary or metastatic malignant neoplasm that affects the colon or rectum. "It has been reported that downregulation of CADM2 mediated by miR-17-5p promotes a malignant phenotype in colorectal cancer." (PMID 37987361, 2023).
kidney clear cell carcinoma (2 papers, 2021 to 2022). "CADM2 activates methylation and/or heterogeneity loss by promoting DNA to contain human kidney clear cell carcinoma." (PMID 34093644, 2021).
Liver fibrosis (2 papers, 2023). "Exosome-derived miRNA of liver fibrosis modulated tumorigenesis by targeting SAMD12 and CADM2 in HCC." (PMID 37228062, 2023). "Subsequently, we investigated whether miR-106a-5p could facilitate the process of liver fibrosis to HCC by modulating the expression of SAMD12 and CADM2." (PMID 37228062, 2023).
mood disorder (2 papers, 2021 to 2023). A cognitive disorder a disturbance in which the person's mood is hypothesized to be the main underlying feature. "Brain expression of NCAM1 and CADM2 was implicated in our colocalization analysis: both regulate neural circuit formation and influence changes in white matter microstructure found in both mood disorders and IBS25,41,42." (PMID 34741163, 2021). "As already mentioned under ENS above, the genes NCAM1 and CADM2 were two genes which regulate neural circuit formation and influence changes in white matter microstructure in IBS and mood disorders." (PMID 36732586, 2023).
cervical cancer (1 paper, 2021). A primary or metastatic malignant neoplasm involving the cervix. "Some hotspot genes (e.g., KLF5, LRP1B, and KLF12) have previously been described in cervical cancer, and others (e.g., CADM2, CEP19, CSMD1, and NRROS) are reported for the first time in the present study." (PMID 34885212, 2021).
Corneal astigmatism (1 paper, 2023). "By using a GWAS approach, SNPs near TJP2, PCBP3, CADM2, and TRPM3 were identified to be associated with myopia or refractive errors, and HMG20A and PPP2R2B were associated with axial length and corneal astigmatism, respectively." (PMID 37449273, 2023).
COVID-19 (1 paper, 2024). A disease caused by infection with severe acute respiratory syndrome coronavirus 2. "A comprehensive gene association analysis incorporating MAGMA, PoPS, and SMR identified a correlation between CADM2 and IBS-COVID-19." (PMID 39620219, 2024).
Duchenne muscular dystrophy (1 paper, 2025). Duchenne muscular dystrophy (DMD) is a neuromuscular disease characterized by rapidly progressive muscle weakness and wasting due to degeneration of skeletal, smooth and cardiac muscle. "At the same time, CADM2 gene expression was downregulated in an animal experiment of duchenne muscular dystrophy, which may be related to intercellular adhesion function, and its expression was also associated with other body indexes, such as body mass index and waist circumference." (PMID 40893940, 2025).
endometrial cancer (1 paper, 2022). Primary or metastatic malignant neoplasm involving the endometrium (mucous membrane that lines the endometrial cavity). "Cell adhesion molecule 2 (CADM2), a member of the CADM family, has been found to maintain cell polarity, and previous studies have demonstrated that CADM2 could promote the migration and invasion of cancer cells, including those of endometrial cancer." (PMID 36561840, 2022).
epilepsy (1 paper, 2015). A brain disorder characterized by episodes of abnormally increased neuronal discharge resulting in transient episodes of sensory or motor neurological dysfunction, or psychic dysfunction. "These microdeletions affected 158 protein-coding RefSeq genes and exhibited an enrichment of genes previously associated with epilepsy (NRXN1, RBFOX1, PCDH7, KCNA2, EPM2A, RORB, PLCB1) and neuropsychiatric disorders (DPYD, CADM2, PARK2, GRM8, TSNARE1, TPH2, MACROD2)." (PMID 25950944, 2015).